CACSTL1 (chromosomal aberration CCDC6::RET stimulating lncRNA 1)
Synonyms: CASTL1
Gene: Long non-coding RNA gene on chromosome 14 (71,219,100 to 71,222,724, forward strand). Ensembl gene ENSG00000269945.
Diseases named in the same sentence as CACSTL1 in open-access papers:
CACSTL1 is named in the same sentence as 1 disease in open-access papers, as found by Europe PMC text mining. Sharing a sentence is not in itself a finding about the gene and the disease.
CACSTL1 shares sentences with these, for which no sentence is quoted: papillary thyroid carcinoma (1 paper).